IL15 (interleukin 15)
Diseases named in the same sentence as IL15 in open-access papers (continued):
Sharing a sentence is not in itself a finding about the gene and the disease.
cancer (continued). "NK cell-derived EVs after incubation with IL-15 were shown to increase cell lysis and inhibit the growth of some human cancer cell lines, including TC, but did not affect normal cells." (PMID 35406748, 2022). "TIL-iPS-T were co-cultured with GFP-transduced cancer spheroids at a ratio of 1:1 in phenol red-free D-MEM supplemented with 10% fetal bovine serum, 2 mM l-glutamine, 100 U/ml penicillin, 100 ng/ml streptomycin, 100 U/ml IL-2, 5 ng/ml IL-7, and 5 ng/ml IL-15." (PMID 34099861, 2021). "In the absence of cancer cells, there was a similar, smaller increase of perforin expression with IL-15 and ADU-S100 (17%) and IL-15 alone (14%) compared to the PBS control (2.2%)." (PMID 33777767, 2021). "This functional assay confirmed that the IL-15 and IL-15Rα coding genes delivered by BV were successfully expressed, and the proteins were self-assembled and functionally competent as a secreted form in the B16F10 and CT26 cancer cells." (PMID 34439192, 2021). "Sufficient stimulation from IL-15 could ensure abundant amount of NK cells surrounding the metastasized cancer cells in the TME, which would subsequently secrete IFN-γ to restrain cancer cells in dormant state." (PMID 34831048, 2021). "The mice immunized with 3 × 105 IL-15:IL-15Rα-B16F10-OVA or IL-15:IL-15Rα-CT26-OVA showed similar body weight changes to the no virus-infected cancer cells, indicating the tolerability of BV-based cancer cell immunization." (PMID 34439192, 2021). "The mechanisms by which the ADU-S100 analogue and IL-15 combination affects the NK mediated killing of the cancer cells is not yet clear." (PMID 33777767, 2021). "Although IL-15 is not as effective as IL-10, we demonstrated the potential of IL-15 in cancer immunotherapy." (PMID 33912464, 2021). "Like phenotyping, intracellular staining of cytokines upon co-culture with cancer cells did not prompt any explanations about the enhanced cytotoxicity in IL-2/IL-15-expanded cells." (PMID 32983105, 2020). "In the context of cancer, generating more memory CD8 T cells (for example, through IL-7 or IL-15 pathways) may improve the outcomes." (PMID 33613548, 2020). "The dependence of TERT expression on all three signaling pathways with IL-2 and with IL-15 in CD8 T cells, suggests that any therapies that inhibit MEK/ERK pathways used in cancer patients are likely to affect proliferation of CD8 T cells to a greater extent than NK cells or NK-like cells." (PMID 33537030, 2020). "Importantly, we have previously shown that IL-15 synergizes with components of the HSV-1 molecular structure to induce potent activation of NK cells, leading to increased cytolysis of cancer targets." (PMID 33182232, 2020). "Interleukin-15 (IL-15) is a cytokine that has been shown to expand CD8 T cell and natural killer (NK) cell populations, and therefore has potential for potentiating adoptive immune cell therapy for cancer." (PMID 33537030, 2020). "The combinations of cytokine and ACT are currently being evaluated in multiple clinical trials in a variety of cancer types, including with different doses of IL-2 (NCT02414945, NCT04052334) or using IL-15 and IL-2 as an adjuvant for NK cell infusion (NCT03669172, NCT03213964)." (PMID 33266177, 2020). "Human ILC3s treated with IL-15 and IL-12 initiate the expression of NK cell cytotoxicity markers (Eomes, CD94, CD56 NKG2A, and NKG2C), suggesting a beneficial role for ILC3-NK plasticity in cancer." (PMID 32117199, 2019). "Besides the approved cytokines, there are other cytokines such as IL-12, IL-21, IL-7, IL-15, IFN-γ, IL-8, and IL-18 tested in anti-cancer treatment in clinical trials." (PMID 31179236, 2019). "An earlier study on a rat model with cancer cachexia showed that IL-15 decreases the rate of protein degradation without affecting protein synthesis." (PMID 30426026, 2018).
cancer (continued). "First, Deep IL-15 provides autocrine signaling that drives survival and expansion of antigen-specific CTLs prior to antigen exposure, enabling a more robust CTL response against TAA-positive cancer cells upon encounter." (PMID 30400835, 2018). "Moreover, a new stabilized IL-15 product, the superagonist ALT-803, has shown great potential in cancer." (PMID 28915646, 2017). "Its strong immunostimulatory activity coupled with an apparent lack of toxicity makes IL-15 an exciting candidate for cancer therapy, somehow limited by its short half-life in circulation." (PMID 27356750, 2016). "Since IL-2- and IL-15- pre-activated NK cells may be used in protocols of adoptive immunotherapy in cancer patients, we further investigated the effect of BRAF-i and MEK-i on NK cells that had been pre-activated for 2 days with IL-2 or IL-15." (PMID 27563819, 2016). "In vitro data showed superior anti-cancer activity and degranulation compared to 1633 without the IL-15 moiety and a moderate cytokine release." (PMID 27240402, 2016). "In vivo experiments proved that the IL-15 TriKE and not the BiKE were capable of expanding NK-cells and inducing an anti-cancer response in a xenograft model." (PMID 27240402, 2016). "The novel cellular mechanisms mediating IL-15 nuclear export and secretion in response to TNF may have broad clinical implications for inflammatory diseases and cancer." (PMID 23950892, 2013). "Interleukin-15 (IL-15) holds potential as an immunotherapeutic cytokine because it has been demonstrated to promote both natural killer (NK) cell-mediated and CD8+ T cell-mediated cytotoxicity against cancer cells." (PMID 24312353, 2013). "Analysis of ROC curves indicates that IL-7 (p = 0.0039), but not IL-6 (p = 0.2938) or IL-15 (p = 0.1804) titres were able to distinguish sera from patients with malignancy from those from patients with benign disease." (PMID 21943235, 2011). "As IL-15 has been shown to reduce Treg activities and increase antigen-specific CD8 T cell response in vitro and in vivo, the ex vivo generated DCP-DCs have potential of overcoming DC dysfunctions in cancer patients." (PMID 21106069, 2010). "Notably, IL-15 did not exhibit toxicity in CAR-NKT cell products, whereas it was associated with increased CRS toxicity in cancer patients treated with conventional CAR-T cells." (PMID 39893165, 2025). "For example, CD56bright cells can acquire cytotoxic activity after IL-15 priming, hepatic CD56bright NK cells show reduced cytokine secretion despite their phenotype, uterine CD56superbright cells promote angiogenesis and tissue remodeling, and CD56-CD16+ have been shown to expand in cancer." (PMID 41246357, 2025). "Likewise, IL15 and HGF are known regulators of the inflammatory response in cancer." (PMID 41056512, 2025). "On April 22, 2024, the IL15 super-agonist N-803 (Anktiva) developed by ImmunityBio was approved by the FDA for use in combination with BCG to treat BCG-unresponsive non-muscle invasive bladder cancer with carcinoma in situ." (PMID 39650651, 2024). "In contrast, the elevated levels of IL-15 detected in the non-smoking HNC group could potentially confer a more robust immune defense against cancer, facilitating a more effective battle against the disease." (PMID 38672104, 2024). "While IL-2 is an approved cancer immunotherapy, IL-15 has not yet established clinical benefit." (PMID 38887559, 2024). "Notably, IL-15-/- mice injected IV with cancer cells showed high levels of metastasis, whereas IL-15-/- mice treated with IL-15 showed virtually no metastasis." (PMID 39559362, 2024). "Furthermore, β.anti-NKG2A.IL-15 stimulated PBMCs killed 92% (± 3.62%) of Raji cells as compared to 28% (± 6.91%) for β.anti-NKG2A, emphasizing the requirement of IL-15 for an optimal cytotoxicity against resistant cancer cells." (PMID 37936122, 2023).
cancer (continued). "Therefore, the PD-L1 targeting of IL-15 differentiates KD033 treatment from ICIs, free IL-15, modified free IL-2, or immune-checkpoint inhibitor treatments, and highlights the merit of KD033’s testing in various cancer indications." (PMID 36454338, 2023). "Although IL-15 does not directly contribute to cancer cachexia pathogenesis, the increase in these cells may lead to an augmented immune response associated with IL-15 and potentially serve as a promising biomarker in the treatment of cancer cachexia." (PMID 37755304, 2023). "However, no studies have explored IL-15 in pan-cancer, limiting its possible clinical application, and the present study has explored the relevance by focusing on both prognostic and immunological directions." (PMID 36467072, 2022). "These suggest that the mechanism of IL-15 in cancers are complex and IL-15 may play a negative role in certain cancer types in a specific condition, which will need to be further tested in the future." (PMID 36467072, 2022). "Intra-tumoral IL-15 can also enable T cells to eliminate cancer cells lacking cognate antigens, which could be especially interesting in those lymphocyte-depleted HCCs." (PMID 33923463, 2021). "However, the splenocytes derived from the mice immunized with the IL-15:IL-15Rα-B16F10-OVA vaccine showed a significantly enhanced OVA-specific cytotoxicity against both B16F10-OVA and E.G7-OVA cancer cells compared with those from the groups infected with control BV or no virus at all the ratios." (PMID 34439192, 2021). "Additionally, unlike IL-2, IL-15 does not significantly affect the numbers and function of regulatory T (Treg) cells, which are stimulated by various cancers to induce suppression of CD8+ T cells and NK cells." (PMID 33537030, 2020). "Recent preclinical studies with a novel fusion protein superagonist of IL-15 signaling, termed ALT-803, have demonstrated greatly enhanced proliferation, activation, and lytic capability of NK cells (and CD8 + T cells), leading to significant antitumor activity in various animal models of cancer." (PMID 29354121, 2017). "Furthermore, the utilization of IL15 in combination therapy with other cytokines (e.g. IL-21 or GMCSF), or co-stimulatory molecules (CD40) is a potential avenue to be explored to improve current cancer immunotherapy." (PMID 26822794, 2016). "IL-15 is a key cytokine exhibiting a pleiotropic effect on the development, proliferation and activation of natural killer cells, as well as the proliferation and activation in CD8+ T-cell, therefore being considered as one of most promising molecules for anti-cancer immune therapy." (PMID 26257729, 2015). "IL-15 is a critical factor in the development, proliferation and activation of effector natural killer cells and CD8+ T cells and has been listed as the most promising agent among twelve immunotherapy drugs with a high potential for use in treating human cancers." (PMID 24896845, 2014). "Furthermore, although the current study focused on the influences of DCIL-15-based cancer vaccines on CD8+ T cells, NK cells are also responsive to IL-15, and the impact of DCIL-15-based cancer vaccines on Type-1 NK cells needs to be comprehensively evaluated in future studies." (PMID 25941586, 2014). "However, daily administration of IL15 is not convenient for cancer treatment because the life span of IL15 is short, and thus IL15 must be given by i.m. injection for many days." (PMID 19422685, 2009). "Redirecting IL-15 towards NK cells, as opposed to T cells, may serve to maintain functionality of both Tregs and NK cells and thus minimise autoimmune responses in the presence of enhanced cancer surveillance by the immune system." (PMID 40868162, 2025). "Moreover, identifying the cancer types and patient subgroups that would benefit most from CX3CR1-engineered CAR-T cells, developing reliable biomarkers, and optimizing combination strategies with IL-15 or immune checkpoint inhibitors remain key areas for future investigation." (PMID 40508161, 2025).
cancer (continued). "Moreover, like other cytokines, new engineering approaches are currently tested in cancer immunotherapy, including IL-7 combination with the Fc domain of different antibodies (e.g., anti-PDL1) (WO2019144945A1), antibody fragments or other cytokines (e.g., GM-CSF, IL-15)." (PMID 39447666, 2024). "Fourth-generation CAR-T cells secreting transgenic IL-7, IL-12, IL-15, and IL-18 have been shown, in preclinical trials with solid tumors, to enhance T-cell activation and stimulate the recruitment of innate immunity cells to kill antigen-negative cancer cells in the lesion focus." (PMID 38927974, 2024). "Notably, on July 28, 2022, ImmunityBio reported that the FDA has accepted a biologics license application (BLA) for the IL-15 agonist N-803 (AnktivaTM) for the treatment of non-muscle-invasive bladder cancer (NMIBC) carcinoma in situ patients who had not responded to bacillus Calmette-Guerin (BCG)." (PMID 37483629, 2023). "A recent study indicated that NK cells pre-activated by IL-12, IL-15 and IL-18 suppress graft-versus-host disease but obviously inhibit the generation and function of CD8+ T cells, which could result from mutual competition of IL-2, limiting its value in the field of cancer treatment." (PMID 32762681, 2020). "The observed lack of membrane-bound IL-15 on “gold-standard” IL-4 DCs and their consequent inability to effectively promote NK cell cytotoxicity may have important implications for the future design of DC-based cancer vaccine studies." (PMID 25951230, 2015). "Although IL-15 has recently been acknowledged as a versatile molecule with great potential in cancer immunotherapy and NK cell stimulation, none of these PCC studies evaluated IL-15 activated NK cells." (PMID 28915646, 2017). "Cancer tissue from women not infected with HPV 16 or 18 had higher concentrations of GMCSF (p = 0.004), IL10 (p = 0.037), and IL15 (p = 0.041), when compared to those of women infected with HPV16/18, after adjusting for age, parity and hormonal contraception." (PMID 25810759, 2015). "However, we observed that in PBMC-cancer cell co-cultures, NK cells treated with the ADU-S100 analog, with or without IL-15, had an increased population of dead cells (up to 30% dead cells) in the presence of the 0.5 and 1 μg/ml doses." (PMID 33777767, 2021). "Cytotoxic activity was compared with and without Deep IL-15, and kinetic analysis of CTL function including expansion, activation, and cytotoxicity was used to provide mechanistic understanding of Deep IL-15 impact on anti-cancer cell activity by CTLs." (PMID 30400835, 2018). "However, unlike IL-2, IL-15 does not support regulatory T cell populations or promote activation induced cell death (AICD), both of which may inhibit anti-cancer immune responses." (PMID 26500048, 2015).
infection (320 papers, 2006 to 2026). The state of being infected such as from the introduction of a foreign agent such as serum, vaccine, antigenic substance or organism. "We next compared the effects of IL-15 and NK cell deficiency to those of IFNε deficiency and determined if IL-15 and NK cells are required for IFNε-mediated protection against infection." (PMID 38263527, 2024). "We also used NK cell deficient Il15-/- mice and rIFNε to show that NK cells are the major contributors to IFNε-mediated infection control in vivo." (PMID 38263527, 2024). "Similar to Ifne-/- mice, NK cell deficient Il15-/- mice have reduced IFNγ responses during infection and rIFNε is unable to induce IFNγ responses or protect against infection in NK cell-deficient Il15-/- mice." (PMID 38263527, 2024). "T cell depletion of vaccinated mice at infection was performed to determine the impact of enhanced T cell responses by Wyeth/IL-15/5Flu vaccination on the increased mutational frequency observed after IAV challenge." (PMID 35385318, 2022). "In this study, we analyzed HIV latency establishment in different CD4+ T cell subsets stimulated with interleukin 15 (IL-15), a cytokine that increases both susceptibility to infection and reactivation from latency." (PMID 35499323, 2022). "There was also an increase in mutations over time, from day 3 to day 7 of infection, in Wyeth/IL-15/5Flu–vaccinated groups within HA, NP, PA, and PB2 genes, whereas sequences from S-QIIV vaccination groups remained stable with time when compared with PBS." (PMID 35385318, 2022). "Taken together, these data suggest that, in our experimental system, IL-15 had a positive effect on overall infection in all TSCM, TCM, TEM, and TTM cells, but the susceptibility of naive cells was unchanged." (PMID 35499323, 2022). "The increased infection in CD4+ T cells stimulated with IL-15 was associated with an almost 10-fold increase in the phosphorylation of SAMHD1 on threonine 592 that abrogates its restriction activity." (PMID 35499323, 2022). "We show that IL-15-deficient mice succumb to infection whereas IL-15Rα-deficient mice clear the pathogen as efficiently as wildtype mice." (PMID 34956227, 2021). "Elevated IL-15 in acute HIV regulates the susceptibility of CD4+ T cells to infection, thus playing a crucial role in viral reservoir establishment." (PMID 34578331, 2021). "In this regards, IL-15 SA caused a substantially higher activation of CD4+ T cells (~ 55% CD69 expression) post infection as compared to the sham (~10%) and vehicle treated burn wound infected group (~32%)." (PMID 26859674, 2016). "We included in the study the cytokines known to be induced very early during pathogenic infection, such as IL-15." (PMID 24991927, 2014). "Monitoring of 15 cytokines showed that those, which are known to be increased early in HIV-1/SIVmac pathogenic infections, such as IL-15, IFN-α, MCP-1 and CXCL10/IP-10, were significantly increased in AGMs as well." (PMID 24991927, 2014). "Although the cytokine IL-15 is required for development and the expansion of developing NK cells, other cytokines and signals can cause NK cells to expand and respond to infection." (PMID 25197644, 2014). "CD11c−CD11b+ cells (granulocytes) or CD11c+CD11b− (dendritic cells) in the airways following infection were mostly unaffected by the IL-15 deficiency, with only a small reduction observed at day 4 p.i.." (PMID 22624047, 2012). "In both mouse groups IL-12 was induced upon infection, although mDC-derived IL-12p40/p70 was slightly reduced in IL-15-deficient mice at the 12 h time point." (PMID 20213736, 2010). "However, in SAP patients, IL-15 levels are significantly elevated and are associated with disease severity, organ dysfunction, infection risk, and poor prognosis." (PMID 39958351, 2025).